INS (insulin)
Diseases named in the same sentence as INS in open-access papers (continued):
Sharing a sentence is not in itself a finding about the gene and the disease.
depression (continued). "In T2DM, insulin signaling dysregulation further disrupts 5-HT neurotransmission, creating a bidirectional relationship between metabolic dysfunction and depression." (PMID 40918536, 2025). "The proportion of patients receiving basal plus bolus insulin treatment was lower in the normal, mild, and moderate depression groups compared to the severe depression group." (PMID 40429455, 2025). "Depression scores were found to be significantly higher in individuals using mixed insulin (B = 5.27, p < 0.001)." (PMID 40429455, 2025). "Several studies have reported that depression and excessive alcohol consumption can individually impair glucose metabolism by reducing insulin sensitivity and disrupting insulin secretion." (PMID 40870425, 2025). "One plausible explanation is the potentialconnection between defective brain insulin signaling and depression." (PMID 40916959, 2025). "Incorporating biological markers—such as inflammatory cytokines, cortisol rhythms, or measures of insulin sensitivity—into network models will provide an even more mechanistic understanding of the pathways that link depression and MetS." (PMID 41295264, 2025). "The results of studies investigating the relationship between insulin treatment and depression are controversial." (PMID 40429455, 2025). "The main predictive variables identified were potassium (K), folic acid, alkaline phosphatase (ALP), height, transferrin, weight, body mass index (BMI), triglyceride (Tg), Beck Depression Test score, and insulin levels." (PMID 40284254, 2025). "At the neuroendocrine level, anxiety and depression can dysregulate the hypothalamic–pituitary–target gland axis, promoting secretion of insulin-counterregulatory hormones and consequently impairing glycemic control." (PMID 40949331, 2025). "In general, the model reveals that both demographic (gender, age, BMI) and clinical (type of insulin treatment, HbA1c) variables have significant effects on depression." (PMID 40429455, 2025). "Gut microbiota dysbiosis can induce further pathogenesis of parasitic infection, however studies in post-stroke depression events revealed the intake of insulin increases the abundance of C. sensu stricto in the intestines to promote nutrition uptake." (PMID 40378358, 2025). "Biological factors such as insulin signaling exert effects on depression-related neurocognitive systems, providing support for a causal link from metabolic to mental health." (PMID 40991698, 2025). "Blood insulin levels correlated inversely with depression-like immobility in these animals receiving both ketamine and lithium, and increased insulin signaling in the infralimbic PFC also correlated with behavioral improvement." (PMID 41304907, 2025). "Myo-inositol 2 g/day was also prescribed to improve insulin sensitivity and for anti-oxidative purposes, bearing in mind the experimental applications for anxiety and depression." (PMID 40141399, 2025). "Together, this underscores the potential role of insulin sensitivity in the pathophysiology of depression." (PMID 40991698, 2025). "For example, both persons with PCOS and depressive disorders are commonly reported to evince metabolic disruption, insulin resistance and alterations in the hypothalamic–pituitary–adrenal axis." (PMID 40457354, 2025). "Psychological pressures affect the autonomic nervous system and alter the hypothalamic–pituitary–adrenal axis, which leads to depressive disorder and metabolic abnormalities including visceral fat accumulation and insulin resistance." (PMID 40004942, 2025). "When there is a dysregulation in insulin signaling, it can lead to certain brain disorders, including depression and Alzheimer’s dementia (AD)." (PMID 39518747, 2024). "In particular, excessive consumption of added sugars can disrupt the gut microbial environment, leading to inflammatory responses, insulin resistance, oxidative stress, endorphin and dopamine dysregulation, and ultimately, depression." (PMID 38542687, 2024).
depression (continued). "Previous studies have shown that insulin action in the hypothalamus of patients with major depression is impaired with increased visceral adiposity and decreased lipocalcin levels, which then reduce insulin sensitivity in patients with major depression." (PMID 39054520, 2024). "Impaired brain glucose metabolism and insulin signaling are key pathological features of depression and contribute to its onset and progression." (PMID 39484160, 2024). "The findings revealed that while significant depression did not predict the five-year incidence of DR, the utilization of insulin was strongly correlated with incident major depression in patients with type 2 diabetes." (PMID 38646317, 2024). "In conclusion, it is essential to consider the potential for depression when managing diabetic patients, particularly those undergoing insulin therapy." (PMID 39598055, 2024). "The weakened efficacy of lithium treatment in mood disorder due to the impairment of insulin signaling supports the importance of insulin in the treatment of depression." (PMID 38398483, 2024). "For example, a 4.4% weight loss (75.84 to 72.65 kg) after 12 weeks was noted compared to 1.1% (72.98 to 72.19 kg) in the control group, with the intervention group also showing significant improvements in postprandial insulin levels, hirsutism, and depression." (PMID 39201229, 2024). "There is also a reciprocal correlation between experimental models of depression and insulin resistance as well as between insulin or oral antidiabetic treatment and antidepressant activity in animal models of T1D and T2D." (PMID 38279738, 2024). "Considered together, results supported moderation whereby more severe symptoms of depression predicted greater resistance to insulin, but only amongst those with frequent exposure to urban environmental threats." (PMID 39579357, 2024). "IR is a predictor of non-response to some antidepressants, it seems to be a state-marker of clinical or subclinical depression, moreover, some insulin-sensitizing interventions are beneficial for the treatment of major depressive disorder." (PMID 38563024, 2024). "Recent trials have demonstrated the positive effects of nasal insulin in individuals with schizophrenia, bipolar disorder, depression, smoking addiction, and improving olfaction in individuals with impairment in the sense of smell." (PMID 38441832, 2024). "Glucocorticoids, which exert metabolically opposing effects to insulin, are the allostatic mediators related to metabolic dysregulation and were proposed to link insulin sensitivity and depression in male mice." (PMID 38397124, 2024). "The increased levels of PAI-1, induced by some pro-inflammatory cytokines, glucose, insulin, and cortisol, are reported to associate with PCOS as well as depression." (PMID 39669109, 2024). "Some diabetic patients with confirmed depression were on a combination therapy (insulin and Metformin)." (PMID 37109040, 2023). "Nevertheless, findings from published preclinical and clinical studies indicated that SSRIs are more beneficial compared to other antidepressant types on insulin sensitivity and glucose homeostasis in T2D patients with depression." (PMID 37653558, 2023). "On the contrary, other studies found a higher prevalence and severity of depression among patients who were on insulin." (PMID 39035064, 2023). "During acute episodes of depression, insulin resistance is increased, and insulin has been proposed as a biomarker of the a metabolic subtype of depression." (PMID 38002705, 2023). "Some proinflammatory cytokines and hormones (such as ghrelin, leptin, orexin, or insulin), involved in appetite and weight regulation, are cited among the neurobiological substrates of depression." (PMID 37049408, 2023). "On the other hand, patients with depression have manifested abnormalities of numerous hormones, including thyroid hormones, insulin, and sex hormones." (PMID 37152963, 2023).
depression (continued). "The possible molecular mechanisms associating defective brain insulin signaling with reward system, neurogenesis, synaptic plasticity, and HPA stress axis have been observed in depression." (PMID 37653558, 2023). "We found that the major predictors of clinical efficacy were depression, anxiety, self-esteem, motivation, restrained eating behavior, body shape satisfaction, and insulin resistance." (PMID 38062157, 2023). "Results of a randomized double-blind metformin-controlled trial in patients with polycystic ovarian syndrome and comorbid depression Does pioglitazone improve depression through insulin-sensitization?" (PMID 37101044, 2023). "Two case studies reported a reduction in insulin dose after phototherapy in insulin-dependent diabetic patients with winter depression, suggesting a positive impact on glycemic control." (PMID 36986120, 2023). "Three metabolic hormones—insulin, leptin, and adiponectin—are integral to understanding relationships between inflammation, depression, and brain function." (PMID 37443383, 2023). "Overall, NAC consumption for 12 weeks had promising effects on mental health symptoms (depression and anxiety), insulin resistance, body anti‐oxidative defense system (TAC and GSH), and hs‐CRP levels in outpatients with SUD under MMT." (PMID 36448959, 2023). "Having secondary education and using both insulin and medication increased the likelihood of depression, whereas being a business professional and being physically active reduced the likelihood of depression." (PMID 37237354, 2023). "The aim of the current study was to explore the inter-relationships between cognitive functioning, depression and insulin resistance in cognitively healthy middle-aged adults." (PMID 37236657, 2023). "Patients with Treatment-Resistant Bipolar Disorder who had their Insulin Resistant successfully reversed by metformin saw a statistically significant and clinically significant decrease in their depression rating scale scores." (PMID 36185927, 2022). "Depression as a comorbid condition occurs in a significant proportion of suicide cases in the diabetic population, including those who choose insulin overdose as a way to take their own lives." (PMID 35324747, 2022). "According to the authors, stress-related cortisol and insulin release in the body may stimulate ingestion of energy-dense “comfort foods”, thus improving mood and mitigating effects of stress-induced dysfunction and associated depression via brain opioidergic and dopaminergic neurotransmission." (PMID 36501217, 2022). "In contrast, insulin and leptin resistance affect the normal function of brain tissue, which can lead to depression." (PMID 36387921, 2022). "Aberrant insulin signaling has also been found in other diseases of the nervous system such as depression, with indirect improvements being observed after CBT." (PMID 36352383, 2022). "Rural residence (OR 1.94), presence of any diabetic complication (OR 3.125), insulin use (OR 2.687), and presence of major depression (OR 4.753) were positive predictors of DD." (PMID 35065623, 2022). "Depression directly impairs the ability to produce or use insulin through hormonal, neuronal, and immune system changes." (PMID 36078289, 2022). "A literature review revealed limited information on the effects of probiotic administration on depression, anxiety, sleep quality, lipid profiles, insulin sensitivity, inflammatory factors, and oxidative stress biomarkers in opioid-related disorder." (PMID 35685534, 2022). "Family-XIII-AD3011-group, as a conditionally pathogenic bacterium, causes excessive insulin secretion in gut microbiota dysregulation or other pathogenic bacteria’s excitation states, thus resulting in hypoglycemic symptoms that may be related to depression and metabolic disturbance." (PMID 35739841, 2022).
depression (continued). "Future studies of insulin-sensitizing medications should measure metabolic markers and study the links between changes in metabolic markers and changes in depression." (PMID 36347837, 2022). "The autopsy case review revealed a plausible suspicion of insulin intoxication by the forensic pathologist, with a history of depression noted, alongside the body presenting with multiple injection marks on the abdomen." (PMID 36676928, 2022). "According to previous studies, PCOS-induced depression can be effectively treated with acupuncture, oral contraceptives, psychological therapy, and insulin sensitization agents." (PMID 36117653, 2022). "For example, failure to self-manage insulin dosages appropriately negatively impacted P25’s mood, while being in control of his T2D also helped him self-manage his depression." (PMID 35210344, 2022). "An analysis of a series of cases conducted in Japan revealed a pre-incident mental illness (depression, alcohol addiction, borderline personality disorder, autism-related disorders, delusional disorders) in 64% of suicidal overdoses of insulin." (PMID 35324747, 2022). "Some studies have noted that insulin therapy improves symptoms of depression in patients with type 2 diabetes, whereas other studies have noted that it does not." (PMID 36552776, 2022). "Insulin signaling associated with glucose metabolism in neurons was identified, which is consistent with findings that intravenous insulin improves mood and cognition, and depression subjects have glucose disruption." (PMID 33746756, 2021). "With respect to other profiles, high self-appraisal patients showed differential sociodemographic and clinical variables: low rates of financial difficulties, insulin treatment, comorbidities, and depression." (PMID 33481883, 2021). "For depression-like behaviors, SHBG, FAI, age, WC, WHR, number of deliveries, fasting insulin, FPG, and HOMA-IR were significant risk factors with odds ratios of 0.203, 1.268, 1.639, −0.403, 46.293, −4.199, −2.805, −11.709, and 10.749, respectively (P < 0.05)." (PMID 34744814, 2021). "GPR39 plays an important role in wound healing, depression, inflammatory bowel diseases, alcohol use disorder, insulin secretion and several cancers." (PMID 34645465, 2021). "Compared with controls, cases were more likely to have depression (27.6% vs. 16.7%), and to use antiplatelet agents and insulin." (PMID 34912022, 2021). "Depression in T1D is known to affect adherence to insulin treatment, leading to worse metabolic outcome, higher rates of glycaemic decompensation, and more hospital admissions." (PMID 33483854, 2021). "From 2010 to 2020, the annual publications on insulin and depression included a total of 3,131 related articles." (PMID 34366917, 2021). "Although, there is no article explaining the direct relationship between exercise, depression, and insulin." (PMID 34366917, 2021). "Research of the effects of changes of sex hormone and insulin levels in female perinatal and menopausal on depression will increase." (PMID 34366917, 2021). "Insulin signaling has been shown to regulate the dopaminergic and serotonergic systems, which are pathways that play a key role in depression." (PMID 34366917, 2021). "Considering sociodemographic and clinical variables, limited engagement patients were somewhere between the high self-appraisal and strained profiles when it came to taking insulin treatment and depression." (PMID 33481883, 2021). "Strained patients had higher scores than high self-appraisal and limited engagement patients for financial difficulties, taking insulin treatment, comorbidities, depression, and BMI." (PMID 33481883, 2021). "No strong evidence of a causal effect of any of the glycaemic traits was found testing seven other psychiatric phenotypes, although there was relatively weaker support for a protective effect of fasting insulin on depression." (PMID 32920595, 2021).
depression (continued). "The analyses indicated significant χ2 coefficients for insulin treatment, comorbidity score, depression screening, and financial insecurity." (PMID 33481883, 2021). "This study’s findings suggest that changes in insulin sensitivity and adiposity starting from childhood may have disorder-specific associations with psychosis and depression and represent targets for prevention and treatment of cardiometabolic disorders in people with psychosis and depression." (PMID 33439216, 2021). "Recent studies have highlighted role of insulin and insulin receptors in depression and other mood disorders." (PMID 34121997, 2021). "The profiles were differently associated with the variables of perceived financial insecurity, taking insulin treatment, having depression, and the congruence of the care received with the Chronic Care Model." (PMID 33481883, 2021). "We also explored the associations among blood and saliva biomarkers (pro-inflammatory cytokines, vitamin D, insulin, leptin, and cortisol) with measures of executive functions depression, and social anxiety." (PMID 31973090, 2020). "The incidence of depression has gradually increased in recent years, and the effects of insulin on depression are widely studied." (PMID 32281722, 2020). "Patients on both oral hypoglycemic drugs and insulin were found to be more likely to have depression than among those on oral hypoglycemic drugs only (OR = 6.78, CI: 4.1–11.2, P = 0.0001)." (PMID 32637427, 2020). "The first described that 4 weeks of exercise training or the exercise mimetic AICAR improved glucose homeostasis and depressive behavior in a model of depression-like and insulin resistance states by co-treatment with HFD and corticosterone." (PMID 33066464, 2020). "She abused insulin, both omission and overdose, was highly suicidal, and suffered from comorbid oppositional behavior, depression and anxiety." (PMID 32184745, 2020). "As early as 1980s, many evidences proved that insulin influenced depression and functional insulin receptors were widely present in the brain." (PMID 32281722, 2020). "Oral antibiotics metronidazole or vancomycin can enhance insulin signalling in the brain and relieve depression." (PMID 32281722, 2020). "There was a significant improvement in depression scores, in addition there were significant improvements in insulin and CRP values and in oxidative stress parameters in the active treatment group compared to the placebo group." (PMID 32858844, 2020). "The results showed that the Hospital Anxiety and Depression Scale (HADS)-B (depression) scores were lower in the basal/bolus insulin group at 1 and 3 months compared to baseline, although the change at 6 months was not significant (p = 0.06)." (PMID 32971941, 2020). "Higher fasting blood sugar level, diabetic complication, history of hospital admission, low medication adherence, and taking both insulin and oral antidiabetic medication were found to be strong predictors of prevalence of depression among DM patients." (PMID 33145110, 2020). "Higher fasting blood sugar level, diabetic complication, history of hospital admission, low medication adherence, and taking both insulin and oral antidiabetic medication were found to be strong predictors of prevalence of depression among diabetic patients." (PMID 33145110, 2020). "CREB1 regulates gluconeogenesis, lipid metabolism, and insulin signaling pathways, and the activity of its transcriptional promoter is associated with the pathogenesis of TD2, adipogenesis, and major depressive disorder." (PMID 32316129, 2020). "A decrease in the introversion and anxiety scores, as well as a decrease in depression and anger, confirms that intranasal insulin improves depression." (PMID 32281722, 2020). "We also explored the possible associations among some of the essential blood and saliva components (cytokines, insulin, leptin, cortisol, and vitamin D) with measures of depression, social anxiety, and executive functions." (PMID 31973090, 2020).